IL4 (interleukin 4)
Diseases named in the same sentence as IL4 in open-access papers (continued):
Sharing a sentence is not in itself a finding about the gene and the disease.
food allergy (continued). "In the context of food allergy, MC-derived IL-4 is important for the induction of Th2 responses in vivo and acts directly on B cells to drive germline transcription and IgE isotype switching." (PMID 38919913, 2024). "The critical role of IL-4 in driving Th2 and suppressing regulatory T cell (Treg) responses in food allergy has been demonstrated using mice harboring a disinhibited form of the IL-4 receptor (Il4raF709)." (PMID 38919913, 2024). "We show that food allergy–primed TFR cells specifically upregulate IL-4 gene transcription and produce functional IL-4 that promoted IgE responses both in vitro and in vivo." (PMID 39377224, 2024). "To further understand the nature of IL-4–expressing TFR cells in our food allergy model, we sorted TFR cells from the mLNs of naive and PCT-sensitized mice and performed bulk RNA-Seq." (PMID 39377224, 2024). "We determined that IgE responses are dependent on a high level of IL-4 produced by follicular T cells in the GC, explaining the need for IL-4 produced by TFR cells in the food allergy response." (PMID 39377224, 2024). "Here we have shown that TFR cells produce substantial Il4 mRNA and functional IL-4 protein in the context of a food allergy model that involves allergic sensitization via the gut." (PMID 39377224, 2024). "This has been shown to occur through inhibition of Tregs by ILC2s via IL-4 and promotion of mast cell activation in an experimental model of food allergy where expansion of ILC2s was IL-33 dependent." (PMID 39132724, 2024). "Even if this is not the case, the Chatila study provides clear evidence that Foxp3+ T cells develop into IL-4–expressing cells in food allergy and that this IL-4 can drive IgE responses." (PMID 39377224, 2024). "To gain a deeper insight into the role of IL-4 in the IgE response in the PCT food allergy system, we analyzed the timing of when IL-4 was critical for IgE production in our food allergy model." (PMID 39377224, 2024). "Nonetheless, these data support the larger idea that Ag-specific IgE is highly sensitive to the levels of IL-4 secreted by both TFH and TFR cells and also show that TFR-derived IL-4 is important for the IgE response in the food allergy model." (PMID 39377224, 2024). "In summary, we found that TFR cells produce nearly comparable levels of IL-4 as TFH cells in this peanut-based food allergy model." (PMID 39377224, 2024). "Strikingly, we found that the repressive TFR cells that develop in allergic airway disease also upregulate Il4 gene expression like TFR cells in the food allergy model." (PMID 39377224, 2024). "Our data support the idea that a unique signaling pathway in TFR cells is induced in the food allergy response that can upregulate the expression of AP-1 and other Il4–promoting transcription factors, leading to high-level Il4 expression." (PMID 39377224, 2024). "The cytokine IL-4 drives IgE class-switch, and this provides an explanation of how type 2 T cells contribute to the pathophysiology of food allergy." (PMID 36880703, 2023). "Conversely, treatment with BDMC in a mouse model of food allergy reduced serum levels of the Th2 cytokines IL-4, IL-5, and IL-13 by less than 30%, while increasing IFN-γ levels." (PMID 37998337, 2023). "The activity of probiotic (Lactobacillus murinus) against food allergy showed that oral administration attenuated allergen-induced diarrhoea, mast cell activation, serum IgE and IL-4 production by splenocytes." (PMID 35296330, 2022). "Today, researchers can consistently identify and replicate genetic loci associated with food allergies, such as the common STAT6, IL-10, CD14, IL-12 receptor b1, IL-4, TLR9, and FLG." (PMID 35281070, 2022). "In the study of human umbilical cord-derived MSCs in the food allergy model, allergic symptoms and IL-4, TNF-α mRNA levels, inflammatory cells, and goblet cells in the colon were decreased by MSCs and MSC-CM." (PMID 35203718, 2022).
food allergy (continued). "In food allergies, IL-4 is produced by basophils and IL-33-stimulated group 2 innate lymphoid cells (ILC2s) in addition to Th2 cells." (PMID 35159139, 2022). "Given that IL-4Rα on mast cells plays a critical role in this model, it can be assumed that basophil-derived IL-4 acts on mast cells to aggravate food allergies." (PMID 35693800, 2022). "In IgE-mediated food allergies, IL-4 and IL-13 can promote allergen-specific immunoglobulin E (IgE) antibody production and intestinal allergic inflammation." (PMID 35769569, 2022). "In a mouse model of food allergy, IgE-dependent MC activation, and IL-4 production from MCs, are essential for intestinal Th2 responses and allergen-specific IgE production." (PMID 34156030, 2021). "Nevertheless, IL-4 concentration, a key cytokine in the pathomechanism of food allergy, was significantly lower in the former group, confirming the protective effect of the transferred CD4+ T cells." (PMID 34207474, 2021). "In food allergy, IL‐4 is critically involved in allergic sensitization and promotes IgE class switching." (PMID 34429871, 2021). "Animal food allergy models rely on IL-4-mediated immune responses, and IL-4 can decrease Treg-mediated tolerance, which is a critical mechanism of food allergies." (PMID 34177881, 2021). "For instance, IL-4 promotes Th2 polarization and IgE class-switch in both mice and human food allergy." (PMID 33362786, 2020). "In a murine model of food allergy, IL-33 and MCs promote inflammation in the gastrointestinal tract through IL-4 production by IL-33–stimulated ILC2s, as IL-4 blocks the generation of allergen-specific regulatory T (Treg) cells." (PMID 32226609, 2020). "Previous studies have reported a role for basophil-derived IL-4 in epicutaneous food antigen sensitization and food allergy in mice." (PMID 31369572, 2019). "Studies have also shown increased IL-4 secreting T-cells in PBMCs isolated from humans with food allergy compared to control patients." (PMID 31164117, 2019). "Severe infiltration of CD4+ T cells and over production of the Th2 cytokines, including IL-4, IL-5 and IL-13 have been documented in the intestinal mucosa of humans and mouse models of GI food allergy." (PMID 31164117, 2019). "Conversely, studies in humans and mice with food allergy have demonstrated increased IL-4 and TNF-alpha and decreased IL-10 concentrations." (PMID 31164117, 2019). "In these tissues, the food allergy induction increased the secretion of Th2-cytokines, such as IL-4, IL-5, and IL-13." (PMID 28702458, 2017). "We identified two groups of SNPs covering IL5/RAD50 and IL4/KIF3A, which were significantly associated with food allergy." (PMID 29051540, 2017). "ILC2-derived IL-4 promotes the development of experimental food allergy by dampening regulatory T cell function, which can directly suppress mucosal MC function." (PMID 27853507, 2016). "The Th2-related cytokines IL-4, IL-5, and IL-13 were increased in mLNs from food allergy-induced mice." (PMID 27445434, 2016). "In another study using mice expressing a gain-of-function mutation of IL-4 receptor α chain (Il4raF709), ILC2s are found to produce some IL-4 in response to IL-33 stimulation in a mouse model of food allergy sensitized with staphylococcal enterotoxin B41." (PMID 27853507, 2016). "These effector cells then release a collection of Th2 cytokines (IL-4, IL-5, IL-9, IL-13, IL-15 and IL-18) that are organized in the intestinal immune system for prompting food allergy or anaphylactic immune responses upon successive exposure to the antigen." (PMID 27840774, 2015). "These effector cells, through exposure to an array of Th2 cytokines (IL-4, IL-5, IL-9, IL-13, IL-15 and IL-18) in the intestinal immune system, are primed for food allergy or anaphylactic reactions upon subsequent antigen exposure." (PMID 27840774, 2015).
food allergy (continued). "The known mechanism involved in IgE-dependent food allergy is attributed to the generation of Th2 cells that produce IL-4 with further generation of IgE and IgG1 antibodies." (PMID 22162714, 2012). "A decrease in IL-4 is believed to impair the development of food allergy and the aversion to antigen." (PMID 22091390, 2011). "Production of IL-4 and levels of specific IgE/IgG1 antibodies correlate with aversion to antigen induced by food allergy in mice." (PMID 22091390, 2011). "The mRNA expression levels of the cytokines IL-4 and IL-6 were significantly increased in the jejunum of the food allergy animals (P = 0.002 and P = 0.005, respectively)." (PMID 19450258, 2009). "We have previously shown that ST2-/- mice exhibit reduced IL-4 responses during food allergy which may affect the development of antigen-specific IgE." (PMID 39935481, 2025). "Furthermore, it has been found that chitosan oligosaccharides protect against shrimp protomyosin‐induced food allergy by downregulating IL‐4, IL‐5, and IL‐13 and upregulating interferon (IFN)‐γ." (PMID 40901656, 2025). "Interleukin-4 (IL-4) plays an important role in food allergy." (PMID 41005294, 2025). "Food allergy induction in epicutaneously sensitized mice or mice with alterations in IL-4 signaling was attenuated in ST2-/- mice, suggesting that IL-33-mediated signals are critical for the development of oral anaphylaxis in mice, and that IL-33 promotes food anaphylaxis by targeting MCs or ILC2s." (PMID 39935481, 2025). "IL-4 can mediate food allergy by inhibiting regulatory T cell function." (PMID 40005151, 2025). "Furthermore, we and others have shown that various Th2-derived cytokines such as IL-3, IL-4, IL-9 and IL-10 can have critical roles in promoting MC activation and function during food allergy." (PMID 39935481, 2025). "Therefore, apart from TFR cells being a key source of IL-10 that can promote IgE in food allergy, TFR cells are also a key source of IL-4 that can promote IgE in food allergy." (PMID 39377224, 2024). "The expression of IL4 induced by allergens in patients clinically allergic to milk and sensitized with IgE to milk and peanuts suggests a key role of signaling mediated by this cytokine in food allergies." (PMID 39203933, 2024). "WT, Il4+/–, and Il4–/– mice were thus sensitized for food allergy using PCT." (PMID 39377224, 2024). "Overall, we found that TFR cells strongly upregulate IL-4 specifically after food allergy sensitization but that the gut environment may be especially primed for induction of IL-4 in TFR cells." (PMID 39377224, 2024). "Our results additionally indicate that the levels of IL-4 and IL-4–producing follicular T cells are both critical for IgE responses, providing an explanation for why TFR cell–derived IL-4 may be required for the development of IgE in food allergy." (PMID 39377224, 2024). "Thus, TFR-derived IL-4 promotes the Ag-specific IgE response in this food allergy model but has little effect on the IgG1 response." (PMID 39377224, 2024). "While both IL-4 and IL-10 are important in this food allergy model, IL-4 is a primary regulator of IgE and may play a more dominant role in the IgE response than IL-10." (PMID 39377224, 2024). "In this model, IL-4 produced by basophils plays a key role in the food allergy pathogenesis." (PMID 35693800, 2022). "Individuals with food allergies typically develop Type 2 responses to the allergen, including the production of a number of pro-inflammatory cytokines that drive allergic responses, such as interleukin (IL)-4, IL-5, IL-9, and IL-13 from Th2 and ILC2 cells." (PMID 35769569, 2022). "Since it has not been clearly defined which segment of the intestine is involved in food allergy-induced type 2 immune responses, we investigated the gene expressions of IL-4, IL-5, and IL-13 in the duodenum, jejunum, ileum, and colon by using quantitative PCR." (PMID 36501013, 2022).
food allergy (continued). "In addition, ILC2s can inhibit the formation of Treg-mediated tolerance by releasing IL-4 and further aggravate food allergies." (PMID 34177881, 2021). "The short‐ and long‐term impact of IL‐4/IL‐13 blockade remain unclear in the context of established food allergy." (PMID 34429871, 2021). "Therefore, there is a great potential for biologics, such as anti-IgE but also the anti-IL-4/IL-13 receptor antibody dupilumab, as they interfere with the IgE-dependent reactions present in food allergy in the long term." (PMID 33634220, 2021). "The reduction in ILC2s in the mice that received the NE vaccines may also be a critical factor for the observed reduction in allergic reactivity, as IL-4 and IL-13 producing ILC2s have also been shown to promote experimental food allergy." (PMID 33717078, 2021). "Moreover, clinical signs of food allergy are significantly reduced after epicutaneous sensitization in mice whose basophils cannot produce IL-4." (PMID 33333859, 2020). "Some studies have also documented decreased T-regulatory cells in humans with food allergy, suggesting this may be the reason for the documented decreased IL-10 and increased IL-4 concentrations in these patients." (PMID 31164117, 2019). "IL-4 promotes IgE upregulation and increases intestinal permeability; therefore, the decrease in IL-4, along with the TCRγδ+ cell increase induced by the cocoa diet, may be beneficial in reducing certain stages of hypersensitivity, such as food allergy." (PMID 28702458, 2017). "Recent studies provided evidence that IL-4/IL-13 pathways play an important role in food allergy." (PMID 29051540, 2017). "Thus, mice expressing a gain-of-function mutation of IL-4 receptor α chain (Il4raF709) are more prone to developing experimental food allergy because of a cell-intrinsic effect of IL-4 in intestinal MC homeostasis." (PMID 27853507, 2016). "Moreover the presence of a food allergy induced further BAL IL-4 and IL-5 increase in HDM-sensitized mice demonstrating a Th2 response enhancement." (PMID 25433406, 2014). "Moreover, the mice with food allergy had increased levels of Th2-related IL-4 and pro-inflammatory IL-6 cytokine mRNAs in the jejunum, whereas the thickness of jejunal muscular layers was not affected." (PMID 19450258, 2009). "We next sought to expand on the previous results showing that IL-4–producing TFR cells could enhance IgE responses by using a BM chimera (BMC) system, where we could compare the function of endogenous IL-4–producing TFR cells versus endogenous IL-4 KO-TFR cells on the food allergy IgE response." (PMID 39377224, 2024). "Thus, the therapeutic inhibition of IL-4/IL-13 signaling with dupilumab is expected to lead to a reduction in the recruitment of intestinal mast cells with consequent attenuation of the clinical expression related to food allergy." (PMID 39203933, 2024). "Next, we tested whether TFR cells produce IL-4 specifically in the food allergy model." (PMID 39377224, 2024). "Therefore, IL-4 is a key determinant of MMC expansion in food allergies." (PMID 35159139, 2022). "In contrast, ILC2-derived IL-4 could block Treg function to promote food allergies." (PMID 34177881, 2021). "In conclusion, our current study has markedly increased our understanding of TFR cells, demonstrating that, in food allergy, TFR cells can produce IL-4 and regulate IgE in a complementary manner to TFH cells." (PMID 39377224, 2024). "A number of biologics targeting ILC pathways, such as dupilumab (anti IL-4/IL-13 receptor), etokimab (anti-IL-33) and tepezulmab (anti-TSLP) have been trialled in food allergy and other atopic diseases [54▪,58,59]." (PMID 39132724, 2024). "To look at this, we analyzed intracellular IL-4 and IL-10 in TFR cells by flow cytometry in the food allergy response." (PMID 39377224, 2024). "Overall, our findings have demonstrated that in food allergy, TFR cells can produce IL-4 and regulate IgE in a manner that augments the role of TFH cells in IgE responses." (PMID 39377224, 2024).
food allergy (continued). "Here we show that in this food allergy response, TFR cells produced IL-4 that promotes the generation of antigen-specific IgE." (PMID 39377224, 2024). "In this study, we found that, in a mouse food allergy model, TFR cells produce levels of IL-4 near the levels of IL-4 produced by TFH cells." (PMID 39377224, 2024). "In food allergy, TFR cells can produce IL-4 and regulate IgE in a manner that is complementary to the role of TFH cells in IgE responses." (PMID 39377224, 2024). "Abrocitinib, an inhibitor of JAK1 that is part of the signaling complex downstream of a number of cytokine receptors including IL-4, IL-13, IL-9, and TSLP, is also in a phase I trial for the treatment of food allergy (NCT05069831)." (PMID 36880703, 2023). "The carotene lycopene reduced the cytokine expression of IL-4, IL-13, and IL-9 by about 60% in an ovalbumin (OVA)-induced food allergy model." (PMID 37998337, 2023). "As a result, we observed that dietary emulsifiers, especially P80, significantly exacerbated food allergy symptoms, with increased OVA-specific IgE induction and accelerated type 2 cytokine expressions, such as IL-4, IL-5, and IL-13, in the colon." (PMID 36501013, 2022). "Taken together, this suggests a critical role for IL-4 derived from TSLP-induced basophils in the sensitization to food allergens in the skin, and the development of food allergy." (PMID 33333859, 2020). "The present data showed that the high levels of specific IgE, IL-4 and TNF-α in the IBD patients with food allergy were down regulated after the therapy of SIT and CB, while the levels of antigen-specific IgG4 were up regulated." (PMID 27499766, 2016). "Moreover, WASp-deficient FOXP3+ Tregs has been shown to drive Th2-mediated intestinal inflammation and food allergy, marked by increased GATA-3, IL-4, and IgE levels." (PMID 41035657, 2025). "We have generated foundational data that could lead to additional therapies for food allergy in patients with AD by targeting S. aureus skin colonization, CD40, IL-33, basophils, and IL-4 signaling." (PMID 41005294, 2025). "In this study, we discovered that, in a mouse food allergy model, TFR cells unexpectedly produce levels of IL-4 very similar to the levels of IL-4 produced by TFH cells and that IL-4 derived from TFR cells can promote Ag-specific IgE responses both in vitro and in vivo." (PMID 39377224, 2024). "Here, we decided to test whether TFR cells produce meaningful levels of IL-4 and, if so, whether TFR-derived IL-4 can regulate the IgE response in our food allergy model." (PMID 39377224, 2024). "IgE responses typically develop in allergic responses that also involve the development of both IL-4–expressing Th2 cells and IL-4–expressing TFH cells (frequently referred to as TFH2 cells), but IgE production in the food allergy model is completely dependent on TFH cells." (PMID 39377224, 2024). "Previous studies reported that elevated mMCP-1 levels in the serum, combined with IL-4 and IL-23α transcription in the SI of OVA mice in our study, suggest that mast cells may play a critical role in food allergy." (PMID 35203718, 2022). "We first examined the gene expressions of IL-4, IL-5, and IL-13 in water-treated mice with or without food allergy." (PMID 36501013, 2022). "While IL-17A signaling has been implicated in both allergic inflammation and PSO, there was less enrichment of genes involved in the proallergic IL-4 and IL-13 responses, despite the fact that patients with SAM syndrome often develop food allergies and have elevated levels of IgE." (PMID 34905516, 2022). "Pathophysiology of non-IgE-mediated food allergy is poorly understood, though IL-2, IL-4, IL-5, IL-13, IL-17, tumor necrosis factor (TNF)-α, and TGF-β are thought to be associated." (PMID 35203718, 2022). "This is the first study that aims to detect the expression of Th2 cytokines (IL-4, IL-5, IL-10, and IL-13) in infants with non-IgE food allergy and to compare it to peer healthy subjects." (PMID 35458127, 2022).